SPAST (spastin)
Diseases named in the same sentence as SPAST in open-access papers (continued):
Sharing a sentence is not in itself a finding about the gene and the disease.
movement disorder (2 papers, 2022 to 2023). Neurological conditions resulting in abnormal voluntary or involuntary movement, which may impact the speed, fluency, quality and ease of movement. "Most research on Spastin has focused on its relationship with movement disorders of HSP." (PMID 35418834, 2022).
neurodevelopmental disorder (2 papers, 2022 to 2025). A behavioral and cognitive disorder with onset during the developmental period that involves impaired or aberrant development of intellectual, motor, or social functions. "Disruption of spastin function can impair neurite outgrowth and synaptic formation, processes increasingly implicated in neurodevelopmental disorders (NDDs)." (PMID 40870017, 2025). "Until more robust evidence is available, we propose that SPAST variants be cautiously considered in the differential diagnosis of early neurodevelopmental disorders when accompanied by subtle motor signs suggestive of pyramidal tract involvement." (PMID 40870017, 2025). "Another report described a patient with a mosaic SPAST mutation and a concurrent 1q21.1 copy number variant (CNV), a genomic region strongly associated with neurodevelopmental disorders." (PMID 40870017, 2025).
psychiatric disorder (2 papers, 2017 to 2024). A disorder characterized by behavioral and/or psychological abnormalities, often accompanied by physical symptoms. "Further, we identify a genotype–phenotype correlation between patients carrying loss-of-function mutations in SPAST and the presence of psychiatric disorders." (PMID 28572275, 2017).
SPAST also shares sentences with these, for which no sentence is quoted: cognitive decline (6 papers); Intellectual disability (5); cerebellar ataxia (4); frontotemporal dementia (4); developmental delay (3); Dystonia (3); infection (3); multiple sclerosis (3); peripheral neuropathy (3); cerebrotendinous xanthomatosis (2); cognitive disorder (2); Friedreich ataxia (2); Huntington disease (2); neuropathy (2); Progressive spastic paraparesis (2); schizophrenia (2); speech disorder (2); spinal muscular atrophy (2); adrenomyeloneuropathy (1); Alexander disease (1); anti-phospholipid syndrome (1); arachnoid cyst of (1); Atrophy (1); autism spectrum disorder (1); autosomal dominant spastic paraplegia (1); autosomal dominant spastic paraplegia 3A (1); axonal motor neuropathy (1); Brain atrophy (1); breast carcinoma (1); Cerebellar atrophy (1).
A further 41 diseases each share a sentence with SPAST in 1 paper.